CXCR4 (C-X-C motif chemokine receptor 4)
Diseases named in the same sentence as CXCR4 in open-access papers (continued):
Sharing a sentence is not in itself a finding about the gene and the disease.
liver disease (10 papers, 2012 to 2025). "C-X-C motif chemokine receptor 4 (CXCR4) is a chemokine receptor that plays a significant role in cellular functions, immune processes, growth and development, and liver disease." (PMID 36267567, 2022). "This review emphasizes the role of CXCR4 and its important cell signaling pathways in the pathogenesis of liver disease and summarizes the targeted therapeutic studies conducted to date." (PMID 34386499, 2021). "An in-depth understanding of CXCR4-mediated signaling pathway and its role in liver disease is critical to identifying potential therapeutic strategies." (PMID 34386499, 2021). "Aberrant CXCR4 expression pattern is related to the migration and movement of liver specific cells in liver disease through its cross-talk with a variety of significant cell signaling pathways." (PMID 34386499, 2021). "This review aims to provide a comprehensive overview of the role of CXCR4 and its ligand in liver disease, including its potential as a therapeutic target, and summarize the therapeutic studies of combined targeting CXCR4 pathway." (PMID 34386499, 2021). "Current therapeutic strategies for liver disease mainly focus on regulating the key functions of specific cells in the liver, in which the CXCR4 pathway plays a crucial role." (PMID 34386499, 2021). "We postulated that CXCR4-using viruses have a more deleterious impact on liver disease than R5-tropic viruses because of their pro-apoptotic effect on hepatocytes and their stimulation of collagen production by HSCs." (PMID 23226258, 2012). "Hence, CXCR4 and its ligand provide potential targets for the treatment of liver diseases, and tumors." (PMID 37338718, 2023). "Indeed, in inflammatory liver disease, most liver-infiltrating lymphocytes express CXCR4, and its intensity is more significantly up-regulated in liver-infiltrating lymphocytes than in peripheral blood lymphocytes." (PMID 34386499, 2021). "Summary of drug studies targeting CXCR4 and its ligand in animal models of liver disease." (PMID 34386499, 2021). "CXCR4, one of the most intensively studied chemokine receptors, is involved in many functions in addition to immune cells recruitment and plays a pivotal role in the pathogenesis of liver disease." (PMID 34386499, 2021). "CXCR4 signaling pathway has a dual role in liver disease; on the one hand, in large liver injury model, CXCR4 can participate in the repair liver damage by mobilizing bone marrow hematopoietic stem cells migrating to the liver parenchyma, or by inducing liver endogenous oval cell proliferation." (PMID 28293639, 2017). "Because CXCL12 and CXCR4/CXCR7 play important roles in liver homeostasis and regeneration, their expression has complex interactions in the pathogenesis of liver diseases." (PMID 38767772, 2024). "Furthermore, up-regulation of CXCR4 in UC-MSCs induced by serum from rats with acute liver failure also promotes the migration and homing ability of stem cells to the injured liver, which may ultimately be used to treat liver disease." (PMID 34386499, 2021). "C-X-C motif chemokine receptor 4 (CXCR4) is a chemokine receptor that has been intensively studied because of its significant role in cellular functions, immune processes, growth and development, and liver disease." (PMID 34386499, 2021).
lymphopenia (10 papers, 2014 to 2025). Reduction in the number of lymphocytes. "In humans, gain-of-function (GOF) mutations in CXCR4 are associated with lymphopenia and hypogammaglobulinemia in the so-called WHIM (warts, hypogammaglobulinemia, infections, and myelokathexis) syndrome." (PMID 38519141, 2024). "Disruption of CXCL12/CXCR4 signaling is also a key step in HSC mobilization by G-CSF.This lead us to suspect a causative role of CXCR4/CXCL12 in the lymphoid progenitors rebound during the profound lymphopenia observed after allo-HSCT." (PMID 24621606, 2014). "It has been shown that transient blockade of CXCR4 signaling resulted in a reversion of circulating T-cell lymphopenia in Cxcr4+/1013 mice." (PMID 39588369, 2024). "CXCR4 GOF mutations alter B-cell development and trafficking resulting in B-cell lymphopenia in mice." (PMID 39588369, 2024). "Our findings support a dysregulation of the CXCL12/CXCR4 chemotaxis of T-helper lymphocytes in HHT patients, potentially linked to their T-helper lymphopenia and susceptibility to infection." (PMID 34906163, 2021). "We provide several elements supporting an alteration in the CXCL12/CXCR4 axis on T-helper lymphocytes in HHT patients, possibly related to their specific infectious risk and T-helper lymphopenia." (PMID 34906163, 2021). "On T-helper lymphocytes, CXCR4 under-expression seems to be a central phenomenon in the idiopathic CD4 lymphopenia, but the infectious profiles are quite different." (PMID 34906163, 2021). "Despite the B cell lymphopenia, CXCR4+/1013 knock-in mutant B cells were shown to be more responsive to immunization, leading to higher accumulation of antigen-specific plasma cells in the spleen though not the bone marrow." (PMID 28928741, 2017). "In addition, CXCR4 antagonism was able to correct the abnormal frequencies and numbers of splenic marginal zone and follicular B cells in Cxcr4+/1013 mice, and ultimately normalize B-cell lymphopenia in the peripheral circulation." (PMID 39588369, 2024). "Moreover, CXCR4 GOF mutations not only affect neutrophils but also B- and T-cell lymphopoiesis and their peripheral trafficking and localization, resulting in B and T-cell lymphopenia." (PMID 39588369, 2024). "In accordance with this, altered lymphoid follicle architecture has been reported in CXCR4 GOF Cxcr4+/1013 mice and in two histopathological reports of lymph nodes from WHIM patients, but the origin of these abnormalities is difficult to interpret in the context of WHIM-associated lymphopenia." (PMID 38519141, 2024). "Aiming to find mechanistic evidence that could better explain these contrasting findings, we hypothesized that WHIM-mutant CXCR4 could be leading to an aberrant B cell activation, which could then contribute to lymphopenia and the subsequent immune impairment in WHIM." (PMID 28928741, 2017). "CXCR4 antagonism corrected peripheral blood CD4+ and CD8+ T-cell lymphopenia in these mice and even restored the circulating CD4/CD8 T-cell ratios to WT levels after 7 days and 28 days of treatment." (PMID 39588369, 2024). "CXCR4 antagonism reversed peripheral T-cell lymphopenia and restored the CD4/CD8 T-cell ratio in Cxcr4+/1013 mice." (PMID 39588369, 2024). "Our data thus indicate that prolonged CXCR4 antagonism can correct splenic T-cell abnormalities and normalize T-cell lymphopenia in peripheral blood in Cxcr4+/1013 mice." (PMID 39588369, 2024).
myeloid leukemia (10 papers, 2006 to 2024). A clonal proliferation of myeloid cells and their precursors in the bone marrow, peripheral blood, and spleen. "In this study, CXCR4 constitutive active mutations–CXCR4-CAMs (N119A and N119S) in K562 (human immortalized myelogenous leukemia) cell line were engineered." (PMID 27832067, 2016). "This mechanistically and more formally establishes a key role for proper NK cell homing to the BM via CXCR4 for treating myeloid leukemia." (PMID 38182818, 2024). "In addition, the angiogenesis/tumor metastasis-associated receptor, CXCR4, targeted by ulocuplumab (Bristol Myers Squibb), a fully humanized antibody that blocks binding of stromal-derived factor 1 (SDF-1) in adult myeloid leukemia has entered phase II trials." (PMID 33329395, 2020). "We assessed CXCR4 expression in U937 and Fujioka, two myeloid leukemia cell lines containing the CALM-AF10 translocation, and compared it with that in Kasumi-1, a myeloid leukemia cell line that does not express CALM-AF10." (PMID 35070954, 2021).
peritonitis (10 papers, 2018 to 2025). Inflammation of the peritoneum (tissue that lines the abdominal wall and covers most of the organs in the abdomen). "Similar results have been obtained in murine models of peritonitis and peritonitis-related sepsis, where selective inhibition of CXCR4 and CXCR7 ameliorates disease, limiting neutrophil infiltration at the inflammatory site in an A2BR-mediated manner." (PMID 39188525, 2024). "The findings demonstrate that the peritoneal administration of both wild-type (WT) and genetically modified adipose-derived mesenchymal stem cells (ASCs) expressing CXCR4 and IL-10 is an effective and safe therapy in this mouse peritonitis model." (PMID 38203690, 2023). "Peritonitis reduced both tight junction proteins and the inhibition of CXCR4 and CXCR7 increased them again." (PMID 32210974, 2020). "To our knowledge, we are the first detecting a link between the SDF-1/CXCR4/7 axis and functional A2B-receptor signaling in acute peritonitis." (PMID 32210974, 2020). "Following our hypothesis that the protective effects of CXCR4- and CXCR7-antagonism in acute peritonitis are linked to A2B-receptor signaling, we performed experiments with A2B–/– animals." (PMID 32210974, 2020). "Several studies have demonstrated an increase in the tissue expression of SDF-1 and its CXCR4 and CXCR7 receptors in the peritoneum, lungs, and liver in mouse models of peritonitis, and as confirmed in vitro." (PMID 36012544, 2022). "PNCs and PNC-related selectins were dampened by specific CXCR4 and CXCR7 antagonism in both of our peritonitis models." (PMID 34948374, 2021). "We evaluated gene expression of the chemokine SDF-1 and its receptors CXCR4 and CXCR7 in various organs and peritoneal tissue during zymosan- and fecal-induced peritonitis." (PMID 32210974, 2020). "To further define the protective role of CXCR4 and CXCR7 antagonism during acute inflammatory peritonitis, we evaluated the expression and release of inflammatory cytokines in peritoneal tissue and peritoneal lavage." (PMID 32210974, 2020). "This was also a characteristic of patients suffering from a non-sterile peritonitis, who showed an infiltration of basophils overexpressing CXCR4 in the inflamed peritoneum, known to secrete large amounts of PGD2 and CXCL1236,37." (PMID 29463843, 2018).
rectal cancer (10 papers, 2010 to 2025). A primary or metastatic malignant neoplasm that affects the rectum. "In rectal carcinoma cells, upregulation of CXCR4 was observed following anti-VEGF antibody treatment and, recently, rituximab was shown to induce upregulation in Burkitt lymphoma cell lines and primary DLBCL cells." (PMID 30774774, 2019). "Stromal CXCR4 (CD184) and CXCL12 expression is associated with distant recurrence and poor prognosis in rectal cancer after chemotherapy." (PMID 21339979, 2010).
T cell lymphoma (10 papers, 2014 to 2025). "Our study identifies a direct mechanism of heteromer-based modulation of CXCR4 activation by S1P/S1P1 in both KARPAS299 T cell lymphoma and primary T cells." (PMID 40012038, 2025). "In B and T cell lymphomas, CXCR4 is constitutively expressed and high CXCR4 levels correlate with poor overall survival." (PMID 28577295, 2017). "CXCR4 expression was modestly reduced (approximately 25% in a 3-h assay) in T cell lymphoma A3.01 cells by BFA." (PMID 24516533, 2014). "Third, CXCR4-targeted RLT may be most promising in patients with T-cell lymphoma, as case series reported favorable outcomes in these otherwise difficult-to-treat patients." (PMID 37290799, 2023). "For CXCR4-targeted PET/CT, promising applications include MM and MZL, whereas refractory T-cell lymphoma may benefit from CXCR4 RLT." (PMID 37290799, 2023). "There is no reported clinical data on the CXCR4-targeted imaging in T cell and NK/T cell lymphomas, except a single case report of mycosis fungoides showing intense uptake of [68Ga]pentixafor." (PMID 32757068, 2020). "However, PTCL-NOS and NK/T cell lymphoma may not present CXCR4 overexpression." (PMID 32757068, 2020).
acute leukemia (9 papers, 2013 to 2024). A clonal (malignant) hematopoietic disorder with an acute onset, affecting the bone marrow and the peripheral blood. "Similar Studies on acute leukemia showed that CXCR4 positivity and polymorphism in the SDF-1 coding gene (SDF-1 G801A) were associated with a higher frequency of extramedullary leukemic infiltration." (PMID 33906294, 2021). "Phase I studies have shown feasibility of adding the CXCR4 antagonist Plerixafor to sorafenib and GCSF in FLT3-mutated R/R AML, or to high-dose cytarabine and etoposide in pediatric patients with acute leukemias or myelodysplastic syndrome (MDS)." (PMID 35083154, 2021). "CXCR4 inhibition has been examined in acute leukemia, both as a potential therapy and as a stem cell mobilizer." (PMID 35070954, 2021). "Previous studies have reported therapeutic effect of CXCR4 inhibition in some acute leukemias in the preclinical setting." (PMID 35070954, 2021). "As such, many groups have studied CXCR4 antagonism as a means to improve outcomes in acute leukemias." (PMID 26360610, 2015). "The aim of this study was to explore the inhibitory effect of one novel peptide targeting CXCR4 on the activity of acute leukemia myelocytic cells." (PMID 25312253, 2014). "CXCR4 inhibitors have been incorporated into different treatment regimens in acute leukemias." (PMID 35083154, 2021). "CXCR4 being a superbly targetable molecule, the potential for combinatorial targeting of CD49d and CXCR4 with antagonists for the (neoadjuvant) treatment of acute leukemia should be considered in light of our novel findings." (PMID 29117236, 2017). "CXCR4 antagonism has been advanced clinically in acute leukemia." (PMID 26360610, 2015). "Overexpression of SDF-1's associated receptor, CXCR4, on malignant lymphoblasts is associated with extramedullary infiltration in patients with acute leukemia, irrespective of total peripheral blood blast count." (PMID 23984125, 2013).
bone metastasis (9 papers, 2009 to 2024). Transfer of a neoplasm from its primary site to bones. "A high level of expression of CXCR4 was significantly associated with a greater risk of bone metastasis." (PMID 30564115, 2018). "CXCR4 expression was positively correlated with leptin receptor levels, and incidence of bone metastasis was higher (62.5%) in the CXCR4 high expression group than in the CXCR4 low expression group (28.12%)." (PMID 32836215, 2020). "Several bone metastasis-associated genes induced by TGF-β were revealed to be an indirect effect, such as RANKL, RUNX2, CXCR-4, CTGF and IL-11." (PMID 26697526, 2015). "CXCR4 expression level correlated with bone metastasis-free survival (correlation coefficient: -0.359, P = 0.018)." (PMID 19508713, 2009). "A receiver-operating characteristic-based approach and logistical regression analysis were used to determine the predictive value of clinicopathologic factors, including CXCR4 expression, in bone metastasis." (PMID 19508713, 2009). "CXCR4 (RR: 5.440; P = 0.023) and UICC T3 stage (P = 0.010) were the independent risk factors that most strongly associated with reduced disease-free survival in patients with bone metastasis." (PMID 19508713, 2009). "Bone metastasis occurs significantly more often in CXCR4 positive patients (13.1%) as compared to CXCR4 negative patients (2.4%; P = 0.008)." (PMID 30564115, 2018).
co-infection (9 papers, 2009 to 2025). "TCRαβ+ DNT cells expressed less CCR5 in HIV/TB co-infection than that in TB (p = 0.014), and more CXCR4 in HIV/TB co-infection than that in HIV infection (p = 0.043)." (PMID 36443691, 2022). "Data shows that chronic morphine treatment in the presence of HIV-1 Tat resulted in significant CNS trafficking of Ly6C+CCR5+ and Ly6C+CXCR4+ following co-infection with systemic S. pneumoniae infection, an effect that was significantly attenuated in both TLR2KO and TLR4KO mice." (PMID 26087960, 2015). "We next investigated whether a CXCR4 dependent T cell tropic HIV-1 isolate (HIV-1LAI) was also differentially regulated by co-infection with CDC1551 and HN878." (PMID 19568431, 2009). "68Ga-Pentixafor has a role in the prognostication of patients and selecting potential candidates for therapies targeting CXCR4, particularly in the setting of HIV co-infection." (PMID 40075611, 2025). "In turn, TB increases the expression of the HIV coreceptors CXCR4 and CCR5 (helping HIV spread during coinfection)." (PMID 39033267, 2024). "Next, LA was tested in a cellular HIV-1/HSV-2-co-infection model and its antiviral activity was compared with the well-known HIV-1 entry inhibitor AMD3100 (a CXCR4 antagonist) and the HSV-2 DNA polymerase inhibitor acyclovir." (PMID 26132818, 2015). "Chronic morphine and HIV-1 Tat, in the context of systemic S. pneumoniae co-infection, differentially modulated induction of TLR2/4, which consequently facilitated trafficking of TLR2 → CD3 + CCR5+ and TLR4 → Ly6C+(CCR5+/CXCR4+) immune cells into the CNS." (PMID 26087960, 2015). "Here we describe the potential direct binding of O. tsutsugamushi to CXCR4 and suggests a potential role for this receptor in scrub typhus pathogenicity, as well as additional mechanisms whereby O. tsutsugamushi may impact HIV co-infection." (PMID 38876107, 2024). "Our study found co-infected with TB increased the CXCR4 expression on TCRαβ+ DNT cells compared with mono-HIV infection, suggesting that HIV/TB co-infection might promote the entry of HIV into TCRαβ+ DNT cells by CXCR4 but not by CCR5." (PMID 36443691, 2022). "In the current study, we explored the contribution of specific chemokine receptors, i.e., CXCR4 and CCR5, in differential leukocyte trafficking into the CNS of mice following chronic morphine, HIV-1 Transactivator of transcription (Tat) protein, and/or co-infection with Streptococcus pneumoniae." (PMID 26087960, 2015). "In addition, co-infection significantly regulated the mRNA expression of several chemokine and chemokine receptor genes, including CCL3 (1.62-fold), CX3CL1 (1.7-fold), CXCL16 (0.56-fold), CCR1 (2.23-fold), and CXCR4 (1.55-fold)." (PMID 25906258, 2015).